CHEK2 (checkpoint kinase 2)
Diseases named in the same sentence as CHEK2 in open-access papers (continued):
Sharing a sentence is not in itself a finding about the gene and the disease.
prostate carcinoma (continued). "The CHEK2 mutation is linked to colorectal and prostate cancer, but its association with endometrial cancer is unclear, and CHEK2 is involved in DNA double-strand break repair, a dysregulated response may lead to tumorigenesis." (PMID 40356752, 2025). "Prostate cancer was also observed in a DFSP case associated with CHEK2 germline VUS p.(Glu64Lys)." (PMID 39669616, 2024). "The CHEK2-associated hereditary cancer syndrome could include gastrointestinal tumors (colon and gastric cancer), prostate cancer, renal cancer, thyroid cancer, sarcomas, and hematological neoplasms (leukemia and plasma cell neoplasms)." (PMID 37239385, 2023). "Checkpoint kinase 2 (CHK2), an important multifunctional enzyme associated with cell cycle arrest and apoptosis caused by DNA damage, has been implicated in multiple tumors such as prostate cancer and liver cancer." (PMID 37260140, 2023). "Germline mutations in CHEK2 have been found in patients with breast, colon, and prostate cancers." (PMID 37862420, 2023). "Mutations found in ATM and CHEK2 genes were associated with aggressive prostate cancer." (PMID 35892882, 2022). "CHEK2 carriers in this cohort also demonstrated high-risk features of prostate cancer." (PMID 35892882, 2022). "Thus, in a Croatian population, CHEK2 P/LP variant carriers were associated with increased risk for early onset prostate cancer, and carriers of the c.1100delC, p.Thr367Metfs15* had increased risk for aggressive PrCa." (PMID 36360192, 2022). "A similar mechanism has been previously suggested for prostate cancer, since patients with pathogenic germline CHEK2 mutations displayed a significantly higher prevalence of the somatic CDK12 mutation than unselected prostate cancer patients from the TCGA cohort." (PMID 35267514, 2022). "Moreover, CHEK2 has been implicated in conferring an increased risk of prostate cancer (PrCa), especially early onset and metastatic PrCa." (PMID 36360192, 2022). "In 2004, Cybulski and colleagues hypothesized that the portfolio of cancers associating with CHEK2 germline mutations reaches beyond breast and prostate cancers and identified associations with few other cancer types." (PMID 33322746, 2020). "Therefore, male carriers of pathogenic CHEK2 mutations, especially from families with multiple prostate cancers, deserve intensified prostate cancer screening which should include an annual PSA test from the age of 40." (PMID 33322746, 2020). "In that study the deletion of exon 9 and 10 in CHEK2 was shown to lead to a premature protein truncation at codon 381 and to evoke a 2-fold increase in the risk of prostate cancer and a 4-fold increase in the risk of familial prostate cancer." (PMID 32211398, 2020). "CHEK2 mutations were less frequent in prostate cancer patients from Japan." (PMID 33322746, 2020). "The results indicated that a CHEK2 (p < 0.001) or a BRCA2 (p < 0.001) mutation may be associated with an elevated risk for a more aggressive type of prostate cancer." (PMID 28874143, 2017). "Although the low number of observations precluded formal statistical assessment, our data may indicate an elevated risk for breast (OR: 2.19, 95 % CI: 0.55–8.75) and prostate cancer (OR: 1.5, 95 % CI: 0.36–6.00) associated with CHEK2 R95*." (PMID 27708748, 2016). "Based on these results, the authors concluded that CHEK2 may contribute to prostate cancer risk because the DNA-damage-signaling pathway probably plays a significant role in prostate cancer development." (PMID 25431674, 2014). "Dong found 28 CHEK2 germline mutations among 578 men with prostate cancer, suggesting that CHEK2 mutations play a role in prostate cancer development, and Cybulski found common mutations, such as 1100delC, IVS2 + 1G > A and I157T, in families with hereditary prostate cancer." (PMID 24986639, 2014).
prostate carcinoma (continued). "In the following, we provide an overview of the current knowledge of the role of a genetic variant, 1100delC, of CHEK2 in prostate cancer risk along with a meta-analysis and discuss the implication for potential translation of this knowledge into clinical practice." (PMID 25431674, 2014). "Both truncating and missense CHEK2 mutations predispose to prostate cancer." (PMID 19401704, 2009). "CHEK2, which is essential for genomic stability, is known to be a multiorgan cancer susceptibility gene and is frequently analysed in tumour diagnostics, e.g. of breast, colorectal and prostate cancer." (PMID 18831734, 2008). "Recently, variants in CHEK2 gene were shown to associate with sporadic prostate cancer in the USA." (PMID 14612911, 2003). "Here, we explored the significance of CHEK2 gene in prostate cancer causation in Finland." (PMID 14612911, 2003). "Recently, mutations in CHEK2 (MIM 604373) were identified in patients with prostate cancer." (PMID 14612911, 2003). "Additionally, our patient with DFSP and the CHEK2 germline variant p.(Glu64Lys) developed prostate cancer, another CHEK2-associated cancer, suggesting that this genetic alteration could be damaging to CHK2 activity and predispose to cancer formation." (PMID 39669616, 2024). "In addition to BC, the following malignancies were detected in five carriers of CHEK2 pathogenic or likely pathogenic germline variants: pancreatic cancer, uterine cancer, prostate cancer, bladder cancer, multiple myeloma, kidney cancer, colon cancer, and thyroid carcinoma." (PMID 33919281, 2021). "Additionally, a 45,000-patient case-control study on specific subset populations found that African men and European men with CHEK2 mutations has increased risk for developing prostate cancer (OR 3.03; 95% CI, 1.53–6.03; p = 0.0006 and OR 2.21; 95% CI, 1.06–4.63; p = 0.030, respectively)." (PMID 32197306, 2020). "Genes associated with prostate cancer at exome‐wide significance include BRCA2, a known risk factor, as well as other breast‐cancer risk genes CHEK2 and ATM for which previous evidence has been more equivocal." (PMID 39749474, 2025). "Here, we validate BRCA2, ATM and CHEK2 deleterious rare variants as significant risk factors, and reproduce the recently described association of SAMHD127 with prostate cancer in UKB and replicate the finding in additional cohorts." (PMID 39971927, 2025). "There were also four concordant P/LPGVs identified in CHEK2, with one case each in breast, pancreatic, brain, and prostate cancers." (PMID 41465149, 2025). "For individuals with a GPV in CHEK2 or ATM, we provide best practice guidance which favours providing information regarding prostate cancer risk at a results appointment with patient-initiated follow-up (PIFU) if and when required." (PMID 41159931, 2025). "For example, in prostate cancer, pathogenic germline variants in DNA repair genes (ATM, CHEK2, PALB2, BRCA2) vary by ancestry; some are enriched or even unique to specific populations, leading to differences in prevalence and risk across groups." (PMID 41573212, 2025). "Rare damaging variants in CHEK2 (OR = 1.69 [1.41–2.01], P = 2.69 × 10−8) and rare synonymous variants in DMD (OR = 0.50 [0.36–0.67], P = 8.6 × 10−7) were associated with prostate cancer risk at the suggestive significance threshold." (PMID 39971927, 2025). "The relatively common loss-of-function c.1100del variant in CHEK2 (rs555607708, ClinVar VCV000128042) imparts a moderate risk of breast and prostate cancer, even in individuals unselected for family history." (PMID 39438716, 2024). "There was also evidence for an excess risk of other cancers in aggregate in CHEK2 PTV carriers, although breast and prostate cancer explained more than 50% of the excess cancer risk, and the remaining excess was only statistically significant in males." (PMID 39209703, 2024).
prostate carcinoma (continued). "Pathogenic mutations in cancer-driven genes like ATM, CHEK2, PALB2, and XRCC2 have been reported to increase the risk of different malignancies, especially breast and prostate cancers." (PMID 38784039, 2024). "For example, while olaparib has been FDA‐approved for metastatic CHEK2‐ and ATM‐mutated prostate cancer; therapeutic benefit in these patients was suboptimal in comparison to patients harboring BRCA1/2 mutations." (PMID 38898688, 2024). "It has been demonstrated that there is an association of germline CHEK2 variants with breast and prostate cancer but some of the data (VUS classification, patients’ geographic distribution, comprehensive CHEK2 mutation analysis) is heterogenous." (PMID 37239385, 2023). "Among 743 Black prostate cancer patients, we identified 26 unique pathogenic (P) or likely pathogenic (LP) variants in 14 genes (including HOXB13, BRCA1/2, BRIP1, ATM, CHEK2, and PALB2) among 30 men, or approximately 4.0% of the patient population." (PMID 36446039, 2022). "BRCA2 variants were the most prevalent at 5.3%, and variants in ATM, CHEK2, PALB2, BRCA1, and RAD51D were also more common among men with lethal prostate cancer." (PMID 36446039, 2022). "This was consistent with previous reports on the inefficiency of PARPi in CHEK2-altered prostate cancer." (PMID 35323355, 2022). "The final cohort comprised 15 confirmed germline mutation carriers with prostate cancer (ATM n = 9, CHEK2 n = 2, HOXB13G84 n = 4)." (PMID 35892882, 2022). "GJB2, MET, MUTYH and VHL mutations ranked top in kidney cancers, and ATM and CHEK2 mutations ranked top for bladder cancer, while ATM and BRCA1 mutations ranked top for prostate cancer." (PMID 36451132, 2022). "Other genes implicated in the development of prostate cancer include those involved in Homologous Recombination DNA repair: BRCA1 in 199452, CHEK2 in 200353,54, ATM in 200455, and PALB2 in 200856." (PMID 35732815, 2022). "Both cancers are also associated with pathogenic variants in male BC susceptibility genes: prostate cancer with the BRCA1/2 and CHEK2 genes and stomach cancer with the BRCA1/2 and CHEK2 genes." (PMID 36115878, 2022). "ATM and CHEK2-associated cancers were D’Amico intermediate or high risk, comparable to our previously published BRCA2 and BRCAX prostate cancer cohort." (PMID 35892882, 2022). "Genetics of prostate cancer have shown population specific features, particularly related mutations in HOXB13, NBN, and CHEK2; however mutations in BRCA2, mismatch repair genes, BRCA1, and ATM appear to contribute to risk in many populations." (PMID 34503195, 2021). "Among 29 patients presenting with prostate cancer, only three patients had a PV (two in CHEK2 and one in MLH1)." (PMID 34326862, 2021). "Mutations in DNA repair genes such as BRCA1, BRCA2, ATM, CHEK2, and PALB2 are of importance in prostate cancer." (PMID 32197306, 2020). "The CHEK2 gene, which has been well-established in breast cancer pathogenesis, also has ties to prostate cancer." (PMID 32197306, 2020). "Germline mutations in the transcription factor HOXB13 and DNA damage repair genes such as BRCA1, BRCA2, CHEK2, as well as the mismatch repair (MMR) genes MSH6 and PMS2, have been shown to increase the risk of prostate cancer, the most common cancer among men." (PMID 32197306, 2020). "Emerging data has also linked several germline DNA mutations to prostate cancer, namely BRCA1, BRCA2, MSH, ATM, PALB2, CHEK2, and MUTYH." (PMID 32957584, 2020). "Malfunction of CHEK2, a tumour suppressor, is involved in breast, ovarian, colorectal, osteocarcinoma, and prostate cancer." (PMID 31041889, 2019). "Supporting this, we found the age at diagnosis among the breast and prostate cancer patients to be slightly lower among the R95* carriers than among the CHEK2 wild-type patients." (PMID 27708748, 2016).
prostate carcinoma (continued). "CHEK2 c.1312G>T (p.Asp438Tyr) was identified in 23 cases and 11 controls from PRACTICAL, all European, providing evidence of association with prostate cancer risk (OR 2.21 (95% CI 1.06 to 4.63, p=0.030))." (PMID 27595995, 2016). "The risk of prostate cancer is known to be elevated in carriers of germline mutations in BRCA2, and possibly also in carriers of BRCA1 and CHEK2 mutations." (PMID 15280931, 2004). "There was consensus that prostate cancer screening advice for males with a GPV in ATM or CHEK2 should be given at the time of diagnosis, including advice to seek a reassessment if there were any further cancer diagnoses in the family or if they have specific questions about their genetic diagnosis." (PMID 41159931, 2025). "At the gene level, our case-control collapsing analysis confirms associations between rare damaging variants in four genes and increased prostate cancer risk: SAMHD1, BRCA2 and ATM at the study-wide significance level (P < 1×10−8), and CHEK2 at the suggestive threshold (P < 2.6×10−6)." (PMID 39971927, 2025). "Additionally, genetic mutations, including BRCA2, BCL6, CHEK2, and others, were also considered valuable predictors of BCR in prostate cancer." (PMID 40660132, 2025). "In addition to TERT, we found rare non-synonymous variants in three genes associated with decreased prostate cancer risk (ANO7, SPDL1 and AR), and three genes associated with increased risk (HOXB13, CHEK2 and BIK)." (PMID 39971927, 2025). "Furthermore, mutations in DNA damage repair genes such as BRCA2, ATM, CHEK2, BRCA1, RAD51, and PALB2 have been implicated in familial prostate cancer." (PMID 40716035, 2025). "For example, the HRD scores of patients with prostate cancer were significantly lower than those of patients with ovarian cancer, and the HRD scores of patients with prostate cancer and BRCA2 mutations were significantly higher than those of patients with ATM and CHEK2 mutations." (PMID 36791952, 2023). "Studies showed a correlation between CHEK2 missense mutations and a higher risk for prostate cancer, but familial clustering had not been demonstrated." (PMID 37021836, 2023). "The most common mutations involved in prostate cancer include BRCA1/2; ATM (odds ratio (OR) = 2.18), HoxB13 (OR = 3.23), genes involved in repairing mismatched genes and genes associated with Lynch Syndrome (OR = 4.87), and CHEK2 (OR = 1.98)." (PMID 33937056, 2021). "Germline or somatic mutations in DNA damage repair (DDR) genes, such as BRCA2, CHEK2, ATM, RAD51D, BRCA1, and PALB2, have been described in around 20–25% of advanced prostate cancer patients, which involved in aggressive disease and poor outcomes in these patients." (PMID 33413230, 2021). "Rare variants in several genes that were initially implicated in risk for breast or ovarian cancer predisposition (e.g., BRCA1, BRCA2, CHEK2, BRIP1, and ATM), as well as the mismatch repair (MMR) genes, have also been reported to increase the risk of prostate cancer." (PMID 33804961, 2021).
prostate carcinoma (continued). "Studies of breast and prostate cancer patients from Japan included analyses in control populations that revealed the presence of pathogenic CHEK2 germline mutations in 0.1% of both female and male noncancer controls." (PMID 33322746, 2020). "A study including over 86,000 patients found that heterozygotes with CHEK2 mutations, were significantly more likely to develop prostate cancer than noncarriers (OR 1.60; 95% CI, 1.00–2.56)." (PMID 32197306, 2020). "A larger cross-sectional analysis of 1328 men with prostate cancer by Giri and colleagues found 15.6% carriers of germline mutations; 10.9% patients carried a mutation in DNA repair genes (BRCA2 > CHEK2 > ATM > BRCA1), increasing the risk of more advanced tumors (Gleason score ≥ 8)." (PMID 33322746, 2020). "Thus far several genes have been associated with prostate cancer risk including HOXB13, NBS1 and CHEK2." (PMID 30036379, 2018). "CHEK2 c.1343T>G (p.Ile448Ser) was observed in 35 cases and 11 controls, all African, participating in PRACTICAL and was also associated with an increased risk of prostate cancer (OR 3.03 (95% CI 1.53 to 6.03, p=0.00059))." (PMID 27595995, 2016). "Therefore, CHEK2 screening would be a useful strategy for prostate cancer among individuals with familial history." (PMID 25431674, 2014). "However, the familial modifying effects for CHEK2 on the risks of breast, colon and prostate cancer observed here were more extreme than those seen in our earlier studies of BRCA1 carriers." (PMID 19401704, 2009). "It has been confirmed that the CHEK2 gene plays a crucial role in the DNA damage response (DDR) pathway encoding the regulatory kinase CHK2 in the HRR of double-strand breaks, and mutations in DDR genes can result in differential responses of prostate cancer to PARP inhibitors." (PMID 41383501, 2025). "The checkpoint kinase 2 (CHEK2) gene (OMIM 604373) coding for CHK2 protein has been reported as a moderate-penetrance, multi-organ cancer susceptibility gene whose alterations increase the risk of different malignancies including breast, colorectal or prostate cancers." (PMID 26506619, 2015). "Similarly, CHEK2 carriers with a family history of colon or prostate cancer may be good candidates for intensified surveillance." (PMID 19401704, 2009). "However, variants in CHEK2 gene alone do not explain the familial clustering of prostate cancer in Finland as the majority of families did not have any CHEK2 alterations." (PMID 14612911, 2003). "Genes linked to prostate cancer susceptibility, including RNASEL, MSR1 and MIC1, found in areas associated with familial prostate cancer, as well as TLR4, MIC1, PON1, BRCA2, CHEK2 and OGG, have been identified as contributors to prostate cancer development." (PMID 38971935, 2025). "For prostate cancer, the cumulative risks by age 80 were 31% (23% to 38%) for ATM PTV carriers and 25% (20% to 29%) for CHEK2 PTV carriers." (PMID 39209703, 2024). "Germline BRCA2-altered prostate cancer patients had the highest HRD scores, germline ATM-altered patients had intermediate scores and germline CHEK2-altered patients had the lowest scores." (PMID 35740616, 2022). "gDNA segregation analysis confirmed a further six prostate-cancer-affected relatives as carriers; a final cohort for analysis contained fifteen patients (ATM n = 9, CHEK2 n = 2 and HOXB13G84E n = 4)." (PMID 35892882, 2022). "For example, most hereditary cancer panels include genes for breast, ovarian and colon cancer – and includes the five main genes for prostate cancer discussed here (BRCA1, BRCA2, CHEK2, ATM, PALB2)." (PMID 35732815, 2022).